LGALS1 (galectin 1)
Diseases named in the same sentence as LGALS1 in open-access papers (continued):
Sharing a sentence is not in itself a finding about the gene and the disease.
leukemia (continued). "Inhibition of Galectin-1 or Galectin-3 activity is likely to be beneficial as a method to chemosensitize BCP-ALL cells and reduce or eliminate residual leukemia cells." (PMID 36430839, 2022). "PROM1, FLT3, CTGF, LGALS1, IGFBP7, ZNRF1, and RUNX2 were found highly expressed in the MLL-R pro-B ALL compared to the other subclassification of leukemia." (PMID 36276286, 2022). "Studies with other stem-like leukemia cells (U937, U937T, and NB4) also confirmed a stimulatory role of galectin-1 in a model of hypoxia-induced granulocytic differentiation." (PMID 32731422, 2020). "LGALS1 and other members of LFMRS model may regulate the homeostasis of lipid metabolism and the progress of leukemia cells." (PMID 38965225, 2024). "Not surprisingly, Oil Red O staining showed that restrained LGALS1 significantly reduced the accumulation of lipid droplets in LSCs and leukemia cells." (PMID 38965225, 2024). "The effects of Galectin-1 inhibition on both BP-ALL cell proliferation and migration suggest both the leukemia cells as well as the microenvironment that protects these cells may be targeted." (PMID 29580262, 2018). "For instance, galectin-1 induces apoptosis of activated T-cells and T leukaemia cell lines but does not affect resting T cells." (PMID 26148207, 2015). "Thus, the Galectin-1 and Galectin-3 that could protect BCP-ALL cells during drug treatment is complicated in terms of origin, and both leukemia cells as well as stromal cells are a possible source of these Galectins." (PMID 36430839, 2022).
neuroblastoma (14 papers, 2012 to 2025). Neuroblastoma (NB) is the most common solid, extracranial childhood tumor. "The same result for galectin-1—inhibiting cell growth—was observed in human neuroblastoma cells, wherein galectin-1 interacted with ganglioside GM1, thereby disturbing cell–cell and cell–stroma interactions and inhibiting cellular proliferation." (PMID 39996781, 2025). "As for galectin-1, it has been shown to reduce the inflammatory response in LPS-activated neuroblastoma cells." (PMID 36008956, 2022). "Another recent study showed that knockdown of LGALS1 can suppress autophagy 46, as well as we observed in neuroblastoma cell by PLK1 inhibition." (PMID 32231733, 2020). "Galectin-1 secretion by neuroblastoma cells was shown to induce T cell apoptosis and inhibit DC maturation." (PMID 24806510, 2014). "The expression of galectin-1 is shown to regulate by the activation of TrkB in neuroblastoma cells and involved in modulating cellular proliferation, survival and migration of malignant cells." (PMID 22911740, 2012). "The knockdown of Galectin-1 enhances cisplatin sensitivity in neuroblastoma cells." (PMID 37433225, 2023). "Human neuroblastoma (SK-N-SH) or rhabdomyosarcoma (RD) cells were infected with EV71 virus to monitor the interaction of virus and galectin-1." (PMID 25706563, 2015). "Galectin-7 acts similarly to galectin-1 in reducing the growth of neuroblastoma cells, without involving classical apoptosis, thereby playing a key role in spontaneous regression of neuroblastoma." (PMID 35677161, 2022). "These evidences suggest that LGALS1 might serve downstream of PLK1 and contribute to the apoptosis induction and autophagy inhibition triggered by BI 2536 in neuroblastoma cells." (PMID 32231733, 2020).
lymphoma (13 papers, 2011 to 2023). A malignant (clonal) proliferation of B- lymphocytes or T- lymphocytes which involves the lymph nodes, bone marrow and/or extranodal sites. "The data confirmed α2,6-linked sialic acid is able to modulate interactions between galectin-1 and cell surface glycans in human lymphoma." (PMID 24589677, 2014). "The balance between galectin-1-mediated and galectin-8-mediated adhesion may be associated with movement of lymphoma cells through ECM." (PMID 25573487, 2015). "The roles of LGALS1 are well studied in some hematologic malignancies, such as chronic lymphocytic leukemia (CLL) and lymphoma, but the understanding of LGALS1 in AML pathology and progression is currently limited." (PMID 36543880, 2023). "HIV infection reduces the expression of highly soluble galectin-1, which leads to a pro-inflammatory but ineffective T cell response that ultimately promotes HIV-associated lymphoma." (PMID 35677161, 2022). "The expression of galectin-9 is far less extensive than that of galectin-1 and galectin-3 in lymphoma." (PMID 35677161, 2022). "It has been demonstrated that galectin-1 in the tumor microenvironment weakens the sensitivity of lymphomas to CD20 immunotherapy." (PMID 35677161, 2022). "The binding of galectin-1 can induce cell death in both T-lymphoma cells and healthy activated T cells." (PMID 30626136, 2019). "Increased endogenous expression of Galectin-1 was observed to protect K562 chronic myelogenous leukemia cells against adriamycin and imatinib, and in a mouse lymphoma model, Galectin-1 inhibited CD20 mAb-dependent, macrophage-mediated cell killing." (PMID 29580262, 2018). "Perhaps, the significant increment in Lgals1 gene expression is due to the fact that the animals are in the suboptimal condition (residual lymphoma)." (PMID 29410666, 2018). "The α-2,6-sialylation inhibited tumor cell apoptosis induced by galectin-1 resulting in a more aggressive behavior of human malignant lymphoma." (PMID 25573487, 2015). "Studies on the roles of galectins in lymphoma have mainly involved galectin-1, -3, -7, and -9." (PMID 35677161, 2022). "Galectin-1 is overexpressed in lymphoma and plays important roles in this cancer." (PMID 35677161, 2022). "Moreover, in a preclinical mouse model of non-Hodgkin lymphoma using anti-CD20 target therapy, the expression of galectin-1 ablated antibody-dependent lymphoma phagocytosis in vitro and lymphoma cell sensitivity to CD20 immunotherapy in vivo." (PMID 29389859, 2018). "This mechanistic model of modulation of cell adhesion to galectin-1 by ST6Gal1 may provide a new concept in understandings the regulatory mechanisms of lymphoma metastasis." (PMID 25573487, 2015). "Moreover, in lymphoma, galectin-1 expression is strongly correlated with resistance to immunotherapy; in fact, galectin-1-overexpressing lymphoma cells blunt antibody-dependent tumor phagocytosis in vitro, and, in vivo, galectin-1 reduces lymphoma cells sensitivity to CD20 immunotherapy." (PMID 29258207, 2017). "As AP‐1 subunit c‐Jun was shown to up‐regulate LGALS1 expression through AP‐1 site in lymphoma cells, we examined the involvement of AP‐1, mainly composed of ATF, Fos and Jun family protein dimers, in IL‐1β‐stimulated LGALS1 expression in Müller glial cells." (PMID 31328390, 2019). "As increased levels of Galectin-1 were reported in serum samples of lymphoma and osteosarcoma patients, we also compared control and ALL bone marrow and peripheral blood plasma samples for Galectin-1." (PMID 29580262, 2018). "Therefore, α2,6-sialylation of cell surface glycans may be associated with inhibitory effect of cell adhesion to galectin-1 regardless of histological types of human lymphoma cells." (PMID 24589677, 2014). "Collectively, these data suggest that cell surface N-glycans can modulate cell adhesive capacity to galectin-1 in lymphoma cells, regardless of histological subtypes." (PMID 24589677, 2014).
lymphoma (continued). "It was also reported that a Hodgkin lymphoma cell line, which expressed galectin-1, had a negative effect on proliferation of CD4 T cells and that this effect diminished when the lymphoma cells knocked down for galectin-1 were added to the co-culture." (PMID 24212939, 2011).
preeclampsia (13 papers, 2005 to 2025). Preeclampsia is a hypertensive disorder of pregnancy that is characterized by new-onset hypertension with proteinuria presenting after 20 weeks of gestation, and depending on mild or severe forms may initially present with severe headache, visual disturbances, and hyperreflexia. "The placental expressions of galectin-1 and galectin-13 were decreased in early pregnancy loss and preeclampsia, whereas the expressions of galectin-3 and galectin-9 were increased in preeclampsia." (PMID 33796532, 2021). "The dysregulation of LGALS1 expression is associated with preeclampsia, and interestingly, maternal serum LGALS1 levels are significantly higher in pregnancies with premature ruptures of the membranes." (PMID 34360662, 2021). "Circulating levels of Lgals1 increase significantly during pregnancy and several studies indicate the potential use of Lgals1 as a biomarker for miscarriage, recurrent fetal loss and preeclampsia (PE)." (PMID 31231368, 2019). "Also, LGALS1 is deregulated by the variant, while the invalidation of this gene triggers preeclampsia-like symptoms in mice." (PMID 38439971, 2024). "Furthermore, an overexpression of galectin-1 was detected in cases of chorioamnionitis and preeclampsia, underlining its role in inflammation." (PMID 37998731, 2023). "The goal of this exploratory study was to establish a technique to noninvasively characterize placental partial pressure of oxygen (PO2) in vivo in the Lgals1 (lectin, galactoside-binding, soluble, 1) deficient mouse model of preeclampsia using fluorine magnetic resonance imaging." (PMID 33483548, 2021). "Galectin-1 is increased in the placenta of patients diagnosed with severe preeclampsia compared to gestation matched controls." (PMID 36311252, 2022). "The goal of this exploratory study was to investigate the potential of 19F MRI to measure placental oxygenation after i.v. injection of a Perfluoro-15-crown-5-ether (PFCE) emulsion in the gal-1 deficient Lgals1−/− knockout mouse, hypothesizing a PO2 deficit in this model of preeclampsia." (PMID 33483548, 2021). "In preterm preeclampsia, PlGF and VEGFR-1 displayed a differential abundance in both soluble and EV fractions, whereas angiogenin, CD40L, endoglin, galectin-1, and TIMP1 were changed only in the soluble fraction." (PMID 41515555, 2025). "Archetypal targets of the R364X mutant compared to the WT cells are the metallothionein complex of genes on chromosome 16 (from 2- to 5.76-fold), LGALS1 (x4.48-fold), or HTRA4 (x22.81), genes known to be connected with preeclampsia." (PMID 38439971, 2024).
gestational diabetes (12 papers, 2021 to 2025). Carbohydrate intolerance first diagnosed during pregnancy. "Galectin-1 has also been associated with gestational diabetes, and a proteomic study identified higher levels of galectin-1 protein content in the placental tissue of women with gestational diabetes (GD)." (PMID 36295832, 2022). "A study on pregnant women also reported that participants develop gestational diabetes when the adaptive increase of galectin-1 is impaired during pregnancy." (PMID 34743218, 2022).
rheumatoid arthritis (12 papers, 2010 to 2026). A chronic, systemic autoimmune disorder characterized by inflammation in the synovial membranes and articular surfaces. "Galectin-1 (Gal-1), an immunomodulatory lectin with anti-inflammatory properties, has been reported to be elevated in rheumatoid arthritis (RA) and systemic lupus erythematosus (SLE)." (PMID 41756270, 2026). "Reciprocal regulation of galectin-1 and galectin-3 has also been observed in sera from patients with rheumatoid arthritis undergoing various treatments, suggesting possible compensatory mechanisms." (PMID 33583770, 2021). "Elevations in synovial fluid galectin-3 have been observed in rheumatoid arthritis, juvenile idiopathic arthritis and experimental inflammatory arthritis in animal models, whereas galectin-1 is thought to be protective." (PMID 30525048, 2018). "Galectin-1 and galectin-3 have both been previously identified in the proteome of fibroblast-like synoviocytes from patients with rheumatoid arthritis." (PMID 29096716, 2017). "Galectin-1 and galectin-3 are proposed to be important intra-articular modulators of inflammation in both osteoarthritis and rheumatoid arthritis." (PMID 29096716, 2017). "For example, although human articular chondrocytes appear to increase galectin expression under inflammatory OA conditions, synovial fluid galectin-1 concentrations are decreased in human OA, juvenile idiopathic arthritis and rheumatoid arthritis." (PMID 29096716, 2017). "Decreased galectin-1 and increased galectin-3 synovial fluid concentrations have been reported in human patients with OA, juvenile idiopathic arthritis and rheumatoid arthritis." (PMID 29096716, 2017). "Furthermore, galectin-1 has been shown to induce chondrogenic differentiation of MSCs from the bone marrow of rheumatoid arthritis patients." (PMID 29096716, 2017).
Arthritis (11 papers, 2010 to 2022). Inflammation of a joint. "Galectin-1−/− mice are more susceptible to collagen-induced arthritis and to experimental autoimmune encephalitis, and galectin-1 retards T cell trafficking to inflamed tissue." (PMID 26216879, 2015). "In addition to this, mice deficient in the Lgals1 gene displayed increased susceptibility to develop autoimmune-like diseases such as autoimmune encephalomyelitis, arthritis, and lupus." (PMID 34262567, 2021). "Opposite and distinct transcript expression with a higher expression in NP compared to iAF was observed for genes associated with initiation of mRNA translation (EIF1), cell-cycle progression (RGCC) and pathophysiology of arthritis (LGALS1)." (PMID 35409356, 2022). "While galectin-1, 3, and 9 has been extensively studied regarding their modulating role in inflammation and arthritis, galectin-2 and -8 have been less studied in these aspects." (PMID 24416634, 2013). "In summary, galectin-1 plays an inhibitory role in the development of experimental arthritis mainly through the induction of T cell apoptosis and skewed type-2 cytokine response." (PMID 24416634, 2013). "In pre-clinical animal studies, administration of galectin-1 or its derivatives ameliorated the antigen-induced arthritis, providing a strong rational for using galectin-1 as anti-RA drugs in the future." (PMID 24416634, 2013). "In a more recent study, galectin-1-deficient mice exhibited increased susceptibility to CIA, with earlier onset of arthritis and more severe manifestations than the wild type mice." (PMID 24416634, 2013). "Some of these genes have been previously implicated inautoimmune disease: PADI2 expression has been demonstrated to correlatewith arthritis severity in mice (Johnsen etal., 2011), LGALS1 damages cartilage via inflammationin osteoarthritis and PLCL2 has been associated with systemic sclerosis." (PMID 29360927, 2018). "Interestingly, galectin-1 cartilage mRNA expression increased proportionally with the severity of arthritis." (PMID 30525048, 2018). "For example, galectin-1 knockout (KO) mice develop earlier onset and more severe collagen-induced arthritis, and galectin-3 KO mice have reduced inflammation and bone erosion in response to antigen-induced arthritis as compared to wild-type mice." (PMID 30525048, 2018). "In recent years, the essential role of recombinant galectin-1 in the control of inflammation has been widely demonstrated in experimental studies for treatment of various diseases, including autoimmune encephalomyelitis, arthritis, hepatitis, autoimmune diabetes, and ulcerative colitis." (PMID 34262567, 2021). "Therefore, intra-articular administration of BMSCs may be a viable method to achieve therapeutic levels of intra-articular galectin-1, even in the presence of joint inflammation." (PMID 29096716, 2017).
colon carcinoma (10 papers, 2009 to 2025). "Previous studies demonstrated in different tumor types, including colon cancer, an association between high galectin-1 expression and poor prognosis." (PMID 30140386, 2018). "A similar study demonstrate that not only galectin-3 but also galectin-1 expression levels correlate with the degree of dysplasia, suggesting that galectin-1 is related to malignant progression, while galectin-8 has been associated with suppressor activity in colon cancer." (PMID 23658855, 2010). "The second drug, shikonin, was reported to induce apoptosis and autophagy in colon cancer cells by targeting galectin-1 and the JNK-signaling pathway; however, its effect on TIMP1 has not been tested." (PMID 36146640, 2022). "Other group showed that direct co-culture with bone-marrow MSCs increased expression of EMT-related genes, e.g. fibronectin, SPARC, and galectin 1 in colon cancer cells (KM12SM)." (PMID 30310111, 2018). "Further analysis found that, in patients with normal CEA concentration, galectin-1 levels predicted positive lymph node metastasis of colon cancer." (PMID 26448934, 2015). "In agreement with our findings, galectin-1 can decrease migration in different cell types including colon cancer cells, smooth muscle cells, and eosinophils." (PMID 19898636, 2009). "Conversely, galectin-1 reduces cell proliferation in colon cancer and HCC by inducing p27 and p21." (PMID 39996781, 2025). "We also found that, in colon cancer patients with normal CEA, galectin-1 could predict more lymph node metastasis." (PMID 26448934, 2015).
COVID-19 (10 papers, 2020 to 2025). A disease caused by infection with severe acute respiratory syndrome coronavirus 2. "The COVID-19-induced hypoxemia determines the increase in a “hypoxia-responsive protein” named galectin 1 (Gal-1), a lectin that plays an important role in pulmonary fibrosis." (PMID 39767173, 2024). "The authors measured serum galectin-1, galectin-3, and prostaglandin E in the samples of 84 patients with confirmed COVID-19, treated in a tertiary hospital in Turkey, and 58 healthy controls." (PMID 34439802, 2021). "Galectin-1 (Gal-1) is a pleiotropic cytokine involved in many immune and inflammatory processes and its role in COVID-19 is still unknown." (PMID 35075140, 2022). "The recent data suggest that galectin-1, -3, -8, and -9 could become valuable biomarkers for the diagnosis and prognosis of lung fibrosis post-COVID-19 and promising molecular targets for the development of new and original therapeutic tools to treat the disease." (PMID 35897786, 2022). "Nasal macrophages had several differentially expressed (DE) genes in patients with COVID-19 versus patients with LRTD that mirrored alveolar macrophage responses (SPP1, LGALS1 and TMSB10), including IFN-γ response genes (HLA-DPB1, HLA-DQA1 and C1QB)." (PMID 39567718, 2024). "Cluster M3 was highly correlated to cluster M4 as indicated by a high Pearson correlation coefficient (r = 0.92) between the 2 clusters, and contains proteins with a similar alteration in COVID-19 cohorts (eg, VWF, leucine-rich α2-glycoprotein 1, galectin-1, and polymeric immunoglobulin receptor)." (PMID 40224277, 2025). "Galectin-1 (Gal-1), a hypoxia-sensitive lectin, is upregulated in IPF and severe COVID-19." (PMID 40343260, 2025).